ACACA (acetyl-CoA carboxylase alpha)
Description:
Cytosolic enzyme that catalyzes the carboxylation of acetyl-CoA to malonyl-CoA, the first and rate-limiting step of de novo fatty acid biosynthesis. This is a 2 steps reaction starting with the ATP-dependent carboxylation of the biotin carried by the biotin carboxyl carrier (BCC) domain followed by the transfer of the carboxyl group from carboxylated biotin to acetyl-CoA.
Synonyms: ACC1; ACC-alpha; ACAC; ACCA; ACCalpha; ACACalpha; Acac1; hACC1; ACACAD; ACC
Tractability: Small molecule: a drug acting on it is in phase 2 or 3 trials; a structure with a bound ligand is known; a high-quality ligand is known; it has a high-quality binding pocket; it belongs to a druggable protein family. PROTAC: ubiquitination databases record sites on it; its protein half-life has been measured; a small molecule that binds it is known.
Target class: Enzyme
Safety:
Unwanted effects reported when the protein is acted on. In parentheses: how it was acted on, where the effect was seen, and who reports it.
Increased, Liver Steatosis (activation; source: AOP-Wiki)
Gene: Protein-coding gene on chromosome 17 (37,084,992 to 37,406,836, reverse strand). Ensembl gene ENSG00000278540.
Subcellular location: Cytoplasm, cytosol
Subcellular location (Human Protein Atlas): Cytosol; Actin filaments; Nucleoli fibrillar center
Pathways (Reactome):
Metabolism: Activation of gene expression by SREBF (SREBP); Biotin transport and metabolism; Carnitine shuttle; ChREBP activates metabolic gene expression; Fatty acyl-CoA biosynthesis
Disease: Defective HLCS causes multiple carboxylase deficiency
Gene Ontology:
Molecular function: acetyl-CoA carboxylase activity; identical protein binding; protein binding; ATP binding; ligase activity; metal ion binding
Biological process: acetyl-CoA metabolic process; fatty acid biosynthetic process; fatty-acyl-CoA biosynthetic process; protein homotetramerization; acyl-CoA metabolic process; lipid biosynthetic process; malonyl-CoA biosynthetic process
Cellular component: cytosol; mitochondrion
Genetic constraint (gnomAD): Loss-of-function variants: 87 observed, 278.07 expected, observed/expected ratio (o/e) 0.31, 90% interval 0.26 to 0.37. The upper end of that interval is the gene's LOEUF score, 0.37, which puts it in group 1 of 6, group 1 being the genes least tolerant of losing a copy. Missense variants: 1,478 observed, 3,017.1 expected, observed/expected ratio (o/e) 0.49, 90% interval 0.47 to 0.51. Synonymous variants: 920 observed, 1,064.1 expected, observed/expected ratio (o/e) 0.86, 90% interval 0.82 to 0.91.
Homologues: Orthologues: chimpanzee ACACA (99% identical), dog ACACA (98% identical), rabbit ACACA (98% identical), guinea pig ACACA (97% identical), rat Acaca (97% identical), macaque ACACA (97% identical), pig ACACA (96% identical), mouse Acaca (96% identical), tropical clawed frog acaca (89% identical), zebrafish acaca (86% identical). Paralogues in human: ACACB (74% identical), PC (13% identical), MCCC1 (9% identical), PCCA (9% identical).
Diseases named in the same sentence as ACACA in open-access papers:
ACACA is named in the same sentence as 100 diseases in open-access papers, as found by Europe PMC text mining. Sharing a sentence is not in itself a finding about the gene and the disease. The quoted sentences say what the papers report.
breast carcinoma (25 papers, 2015 to 2025). "The ACACA gene was also found to be amplified in breast cancer and is associated with reduced survival." (PMID 29342092, 2018). "FASN a multifunctional enzyme plays a key role in biosynthesis of fatty acid and ACACA is known to specifically interact with the protein coded by one of the major breast cancer susceptibility genes BRCA130." (PMID 26632252, 2015). "A number of studies have implicated ACACA activity in the malignant phenotype of breast cancer." (PMID 28412757, 2017). "S-palmitoylation of PHGDH and FASN promotes chemoresistance in breast cancer, while palmitoylation of ACACA and GPX4 influences lipid metabolic reprogramming and ferroptosis resistance, respectively." (PMID 40626019, 2025). "Taken together, these data revealed a mechanism by which ACACA downregulation directed the formation of an immunosuppressive lung PMN in breast cancer." (PMID 36607556, 2023). "Taken together, these results suggest that ACACA inhibition in the lung fibroblasts of the PMN contributes to metastasis of breast cancer." (PMID 36607556, 2023). "IHC staining revealed that the level of ACACA was downregulated in the lungs of the breast cancer-bearing MMTV-PyVT mice." (PMID 36607556, 2023). "In contrast, the FASN inhibitor cerulenin reduced CPT1A expression only in NFYA wild-type cells, suggesting that NFYA regulates breast cancer malignant behavior by controlling de novo lipogenesis by regulating ACACA and FASN expression." (PMID 37268670, 2023). "To evaluate the role of ACACA in the lung metastasis of breast cancer, we generated a doxycycline-inducible ACACA knock-in model (MMTV-PyVT/ACACA)." (PMID 36607556, 2023). "Recent studies found that breast-cancer-associated mutations in BRCA1 disrupt interaction between BRCA1 and phosphorylated inactivated ACACA (pACACA)." (PMID 29342092, 2018). "More recently, it has been demonstrated that silencing of the ACACA gene in human breast cancer cells in long-term culture as a result of RNA interference results in decreased palmitic acid synthesis and the induction of apoptosis." (PMID 28412757, 2017). "ACACA is a target gene of BRCA1, preventing its dephosphorylation through BRCA1 protein banding to it, while BRCA1 is widely known as a breast cancer susceptibility gene." (PMID 27506935, 2016). "However, in breast cancer, inhibition of ACACA leads to the enhancement of Smad2 acetylation, ultimately resulting in epithelial-mesenchymal transition (EMT) and metastasis." (PMID 41169354, 2025). "In breast cancer, ACACA drives resistance to aromatase inhibitors in estrogen-deprived cells." (PMID 41169354, 2025). "Furthermore, induction of ACACA expression in the lungs prevented lung metastasis of breast cancer in vivo." (PMID 36607556, 2023). "This suggests that ACACA may be a critical factor associated with lung PMN formation and may be a therapeutic target for breast cancer." (PMID 36607556, 2023). "Similarly, in human breast cancer cells, including MCF7 and Hs 578T, caused a reduced expressions of ACACA were found in lung fibroblasts in a co-culture model." (PMID 36607556, 2023). "ACACA has been shown to be over-expressed in advanced breast carcinomas and pre-neoplastic lesions that may progress to infiltrating breast carcinoma." (PMID 29342092, 2018). "In addition, ACACA expression is essential to promote breast cancer cell survival." (PMID 25826294, 2015). "Our study not only demonstrates a novel molecular mechanism of PMN formation, but also provides clinical insights into the therapeutic implication of ACACA and CXCL1 to prevent lung metastasis in breast cancer." (PMID 36607556, 2023). "Breast cancer cell lines that overexpress HER2 (SK-BR-3 and BT-474) express higher levels of ACACA than those in which expression of HER2 is relatively low (MCF-7 and MDA-MB-231)." (PMID 28412757, 2017). "For example, miRNA-195 suppressed the proliferation, invasion and metastasis of breast cancer cells via FASN, HMGCR, ACACA and CYP27B1." (PMID 27813492, 2016).
breast carcinoma (continued). "ACACA and FASN are upregulated in HER2/neu-positive breast cancers at the transcriptional and the translational level." (PMID 27464732, 2016). "The role of pro-apoptotic hsa-miR-195 in inhibiting de novo lipogenesis via targeting genes overexpressed in breast cancer (BCL-2, FASN, ACACA, HMGCR, CYP27B1) makes hsa-miR-195 an effective anticancer molecule." (PMID 26632252, 2015). "miR-195 targets de novo lipogenesis genes, a hallmark in cancer cells especially in aggressive tumors, and that are related to the production of cell membranes for rapid cell proliferation through action on overexpressed target genes in breast cancer such as BCL-2, FASN, ACACA, and HMGCR." (PMID 38813102, 2024). "Furthermore, tumour suppression via suppression of ACACA and FASN in breast cancer tissues and potential developmental abnormalities were investigated in Nfyav1-specific knockout mice." (PMID 37268670, 2023). "We further demonstrated that miR-195 also targets genes involved in de novo lipogenesis, it inhibits cell proliferation, migration, and invasion by targeting FASN, HMGCR, ACACA and CYP27B1 thereby potentially opening new avenues for the treatment of breast cancer." (PMID 30932749, 2019). "Our findings provide evidence that microRNA-195 attenuates epithelial-mesenchymal transition (EMT) in breast cancer cells by targeting FASN, HMGCR, ACACA and CYP27B1 and strongly suggest that overexpression of miR-195 may have therapeutic value in treating breast cancer." (PMID 26632252, 2015). "In addition, miR‐195 can directly target acetyl‐CoA carboxylase alpha (ACACA), FASN, HMGCR, and CYP family 27 subfamily B member 1 (CYP27B1) resulting in modulation of de novo GA/cholesterol synthesis and the inhibition of proliferation and invasion of breast cancer cells." (PMID 34766135, 2021).
prostate carcinoma (25 papers, 2013 to 2025). A carcinoma that arises from epithelial cells of the prostate gland. "Down regulation of ACACA expression is associated with the inhibition of malignant progression of prostate cancer." (PMID 34249761, 2021). "ACACA is a key factor in fatty acid metabolism and the interference of ACACA suppresses cellular proliferation and triggers apoptosis in LNCaP prostate cancer cells." (PMID 39859292, 2025). "Our previous research has reported that ACACA knockdown in prostate cancer cells leads to a significant decrease in de novo fatty acid synthesis, which notably inhibits the PI3K‐AKT pathway, causing the cells to experience pronounced metabolic stress." (PMID 40066226, 2025). "In prostate cancer, ACACA downregulation reduces ATP production, disrupts mitochondrial function, and increases ROS levels." (PMID 41169354, 2025). "Herein, we demonstrated that inhibiting the upstream molecule MEK, ERK itself, and specifically ERK2 (MAPK1) all trigger the EMT program, leading to ACACA‐depleted prostate cancer cell migration." (PMID 40066226, 2025). "For example, c-Myc maintains the glycolytic activity and increases the expression of key fatty acid synthesis genes, such as ATP citrate lyase, acetyl-CoA carboxylase alpha, and fatty acid synthase, thus promoting prostate cancer progression." (PMID 39253786, 2024). "Our study elucidates the pivotal role of ACACA and circKIF18B_003 in governing lipid metabolism and overall cellular metabolism in prostate cancer cells." (PMID 38049827, 2023). "Despite the contrasting impacts of ACACA downregulation and circKIF18B_003 overexpression, both appear to play a crucial role in metabolic reprogramming in prostate cancer cells." (PMID 38049827, 2023). "ACACA is relatively more poorly understood, but downregulation in mouse models has been found to suppress prostate cancer progression and lower tumor volume." (PMID 36765634, 2023). "The malignant ability of prostate cancer cells enhanced by overexpression of circKIF18B_003 was reversed by the down-regulation of ACACA." (PMID 38049827, 2023). "ACACA is a protein-coding gene expressed at higher levels in advanced prostate cancer patients than in lower-grade patients." (PMID 37056387, 2023). "HSPB6 was reported to suppress the MAPK family, including JNK and the PI3K/Akt pathway, and the downregulated ACACA curbed prostate cancer growth." (PMID 35516441, 2022). "The expression of ACACA was significantly higher in prostate cancer (n = 492) than in the normal tissues (n = 152)." (PMID 33391420, 2021). "Studies showed that SFN inhibited lipid synthesis by inhibiting key enzymes such as FASN and ACACA in prostate cancer." (PMID 34620841, 2021). "The data showed that the expression level of ACACA was higher in patients with prostate cancer than in healthy controls, which was consistent with the Gene Expression Profiling Interactive Analysis (GEPIA) data." (PMID 33391420, 2021). "Background and aim: Silencing the expression of ACACA inhibits cell proliferation and induces apoptosis in prostate cancer LNCaP cells." (PMID 33391420, 2021). "The result suggested that ACACA influenced the activity of mitochondria, leading to the death of prostate cancer cells via affecting the ability to produce ATP and the mtDNA copy number." (PMID 33391420, 2021). "Then, prostate cancer cell lines with low expression of ACACA were constructed to evaluate the changes in their cell cycle, proliferation, and metabolites." (PMID 33391420, 2021). "Immunohistochemical staining showed that ACACA was mainly expressed in the cytoplasm of prostate cancer cells." (PMID 33391420, 2021). "The cell cycle was blocked and the proliferation reduced in vitro after knocking down ACACA gene in prostate cancer." (PMID 33391420, 2021). "The results suggested that ACACA was vital in prostate cancer, and the down-regulation of ACACA suppressed prostate cancer through inhibiting mitochondrial potential." (PMID 33391420, 2021).
prostate carcinoma (continued). "This study aimed to discover the specific role of ACACA gene in prostate cancer (PCa) DU145 and PC3 cells as well as its effects on mitochondrial potential." (PMID 33391420, 2021). "Inhibition of ACACA by RNAi led to inhibition of LNCaP prostate cancer cell growth and subsequent de novo lipogenesis." (PMID 29156692, 2017). "Silencing of acetyl-CoA carboxylase-α (ACACA) inhibits the proliferation of LnCAP prostate cancer cells, and inhibition of SREBP2 processing was found to reduce the viability of prostate cancer cells, particularly in lipoprotein deficient serum." (PMID 24280005, 2013). "Downregulation of ACACA suppresses the malignant progression of prostate cancer." (PMID 40823088, 2025). "The aim of this study was to validate whether ND630 could control ACACA and lipid reprogramming in prostate cancer by regulating the expression of circKIF18B_003." (PMID 38049827, 2023). "Notably, ACACA has been found to suppress prostate cancer through the inhibition of mitochondrial potential." (PMID 37608254, 2023). "The objective of this research was to figure out whether ND630 could control ACACA and lipid reprogramming in prostate cancer by regulating the expression of circKIF18B_003." (PMID 38049827, 2023). "ND630 could control ACACA and lipid reprogramming in prostate cancer by regulating the expression of circKIF18B_003." (PMID 38049827, 2023). "The expression of ACACA was first detected in a prostate cancer tissue chip." (PMID 33391420, 2021). "The high expression of ACACA gene has a positive correlation with the TNM stage of prostate cancer." (PMID 33391420, 2021). "Studies have shown that silencing the ACACA gene may result in the inhibition of cell proliferation and induction of apoptosis in highly lipogenic prostate cancer LNCaP cells." (PMID 33391420, 2021). "The results confirmed that down-regulation of ACACA in prostate cancer cells affected the mitochondrial potential by mitigating the balance of NAD+/NADH, mitochondria ATP production, mtDNA, and ROS levels, which decreased the proliferation capacity of tumor cells." (PMID 33391420, 2021). "Finally, it has been described in prostate cancer that genetic alterations of ACACA, FASN, and SREBF1 predicted worse overall patient survival." (PMID 33194695, 2020). "Additionally, the silencing of ACACA by RNAi in cell models of breast and prostate cancer impaired tumor cell proliferation and induced apoptosis, suggesting that ACACA is important for tumor cell survival." (PMID 29342092, 2018). "However, the role of ACACA in other prostate cancer cells is not fully understood." (PMID 33391420, 2021). "From the RNA sequencing data analysis, we observed that two pathways closely related to prostate cancer progression, the PI3K‐AKT pathway and the MAPK pathway, were significantly enriched among the differentially expressed genes following ACACA knockdown." (PMID 40066226, 2025). "In prostate cancer, ND630 regulates the expression of circKIF18B_003, thereby achieving the regulation of ACACA and lipid reprogramming." (PMID 41169354, 2025). "A more recent study has found that the knockdown of MBTPS2 expression in human prostate cancer cells impaired cholesterol synthesis and uptake and reduced the expression of key regulators of fatty acid synthesis, FASN and ACACA, through SREBP signaling." (PMID 37958642, 2023). "Depletion of ACACA in prostate cancer cells inhibits the PI3K‐AKT pathway, leading to negative feedback activation of the MAPK pathway." (PMID 40066226, 2025). "Additionally, Lipid synthesis is increased in prostate cancer and Lipogenic enzyme, such as fatty acid synthase (FASN), ATP citrate lyase (ACLY) and acetyl-CoA carboxylase α (ACACA) is highly overexpressed in prostate cancer." (PMID 29163775, 2017).
prostate carcinoma (continued). "Therefore, the present study focused on the other two prostate cancer cell lines DU145 and PC3 by observing their proliferation, cell cycle, cell metabolite changes, and mitochondrial characteristics after knocking down ACACA gene." (PMID 33391420, 2021).